NRIP3 (nuclear receptor interacting protein 3)
Synonyms: C11orf14; NY-SAR-105
Tractability: No criterion of Open Targets' tractability assessment is met for any kind of drug.
Gene: Protein-coding gene on chromosome 11 (8,965,682 to 9,005,288, reverse strand). Ensembl gene ENSG00000175352.
Subcellular location (Human Protein Atlas): Cytosol
Gene Ontology:
Molecular function: protein binding; aspartic-type endopeptidase activity
Biological process: proteolysis
Cellular component: cytoplasm
Genetic constraint (gnomAD): Loss-of-function variants: 28 observed, 22.66 expected, observed/expected ratio (o/e) 1.24, 90% interval 0.91 to 1.68. The upper end of that interval is the gene's LOEUF score, 1.68, which puts it in group 6 of 6, group 1 being the genes least tolerant of losing a copy. Missense variants: 305 observed, 269.47 expected, observed/expected ratio (o/e) 1.13, 90% interval 1.03 to 1.24. Synonymous variants: 128 observed, 107.89 expected, observed/expected ratio (o/e) 1.19, 90% interval 1.03 to 1.37.
Homologues: Orthologues: chimpanzee NRIP3 (99% identical), macaque NRIP3 (98% identical), dog NRIP3 (95% identical), mouse Nrip3 (93% identical), rat Nrip3 (89% identical), pig NRIP3 (89% identical), guinea pig NRIP3 (86% identical), rabbit NRIP3 (72% identical), tropical clawed frog NRIP3 (61% identical), Caenorhabditis elegans ddi-1 (18% identical), Drosophila melanogaster rngo (15% identical). Paralogues in human: NRIP2 (39% identical), DDI1 (22% identical), DDI2 (22% identical), UBAC2 (15% identical).
Diseases named in the same sentence as NRIP3 in open-access papers:
NRIP3 is named in the same sentence as 18 diseases in open-access papers, as found by Europe PMC text mining. Sharing a sentence is not in itself a finding about the gene and the disease. The quoted sentences say what the papers report.
breast carcinoma (4 papers, 2010 to 2024). "NRIP3 was also identified as one of the key molecular targets significantly correlated with the prognosis of breast cancer by bioinformatics analysis." (PMID 32839439, 2020). "As one of the nuclear receptor interacting proteins, NRIP3 has been reported to form a transforming MLL-NRIP3 gene in acute leukemia and to correlate with the prognosis of breast cancer by bioinformatics analysis." (PMID 32839439, 2020). "It has been confirmed by studies that NRIP3 and RASL11B play a role in suppressing cancer proliferation in breast cancer and renal cell carcinoma 31,32." (PMID 32626531, 2020). "NRIP3, TMC5, REEP1 and NKAIN1, whose expression had not previously been described in breast cancer, were also deregulated in the PIK3CA-mutated breast tumors." (PMID 21209903, 2010).
Cirrhosis (1 paper, 2025). A chronic disorder of the liver in which liver tissue becomes scarred and is partially replaced by regenerative nodules and fibrotic tissue resulting in loss of liver function. "However, except NRIP3, no statistical significance was detected in the comparison of early-stage HCC and cirrhosis." (PMID 40375278, 2025).
esophageal cancer (1 paper, 2020). A primary or metastatic malignant neoplasm involving the esophagus. "The relationship between NRIP3 upregulation and the prognosis of esophageal cancer was further analyzed by univariate analysis." (PMID 32839439, 2020).
prostate carcinoma (1 paper, 2024). A carcinoma that arises from epithelial cells of the prostate gland. "Furthermore, two PSA-dependent prostate cancer risk scores were developed (PRISK1 and PRISK2) which combine known PCa risk factors QfPSA, patient’s age, and the amount of plasma cfDNA with methylated RASSF1A, MIR129-2, NRIP3, and SOX8 cfDNA sequences/mL." (PMID 38611002, 2024).
schizophrenia (1 paper, 2024). A major psychotic disorder characterized by abnormalities in the perception or expression of reality. "Within the CGE, genes with high expression specificity for two calretinin (CALB2)-positive sub-populations of developing GABAergic neurons were also enriched for schizophrenia genetic liability (CGE-N-1, marker: NRIP3, and CGE-N-2, markers: BEX2, ARL6IP5, VSTM2A)." (PMID 38869145, 2024).
cancer (3 papers, 2020 to 2024). A tumor composed of atypical neoplastic, often pleomorphic cells that invade other tissues. "We further examined whether NRIP3 overexpression could increase drug resistance to cisplatin since it is a widely used chemotherapeutic drug that causes DNA damage in cancer cells." (PMID 32839439, 2020). "Despite the identification of NRIP3 by bioinformatics analysis and the fact that NRIP3 is highly expressed in many tumors according to the public database, relatively little is known about the role and function of NRIP3 in cancer." (PMID 32839439, 2020). "The axis that NRIP3 upregulates DDI1 via PPARα and then promotes RTF2 removal represents a protective molecular pathway in cancer cells that mediates their resistance to replication stress signals induced by CRT." (PMID 32839439, 2020).
tumor (3 papers, 2008 to 2020). "The gene expression profile across the ESCC tumor samples from TCGA database and normal samples from GTEx indicates that NRIP3 is upregulated in ESCC tumor samples." (PMID 32839439, 2020). "NRIP3 upregulation was significantly correlated with tumor invasion (P = 0.003), lymph node metastasis (P < 0.001) and TNM staging (P < 0.001)." (PMID 32839439, 2020). "In aggregate, our results demonstrate that NRIP3 overexpression facilitates ESCC tumor cell proliferation." (PMID 32839439, 2020). "Five tumor suppressors or suppressor candidates including NRIP3, CYLD, CD9, ATF3 and OXTR were strongly induced by TSA alone." (PMID 18301774, 2008). "When NRIP3 was silenced in EC9706 cells with shRNAs, tumor growth and weight decreased compared with those in control cells." (PMID 32839439, 2020). "In this study we found an important role of NRIP3 in progression and CRT resistance of ESCC tumor cells." (PMID 32839439, 2020). "qRT-PCR was performed to evaluate the mRNA level of NRIP3 in 40 pairs of ESCC tumor and nontumor tissues." (PMID 32839439, 2020). "In 273 informative paired tissues, NRIP3 upregulation was detected in 176 (64.47%) tumor tissues compared to paired nontumor tissues (P < 0.05)." (PMID 32839439, 2020). "Based on our previous cDNA microarray data of ESCC16, NRIP3 was upregulated in ESCC tumor tissues compared with nontumor tissues." (PMID 32839439, 2020). "NRIP3 was upregulated in 57.5% (23/40) of ESCC tumor tissues compared with nontumor tissues (T/N ≥ 2)." (PMID 32839439, 2020). "NRIP3, TMC5 and REEP1 are differentially expressed in various other tumor types." (PMID 21209903, 2010).
NRIP3 also shares sentences with these, for which no sentence is quoted: leukemia (2 papers); acute leukemia (1); acute lymphoblastic leukemia (1); Anxiety (1); breast tumors (1); colorectal cancer (1); hepatocellular carcinoma (1); lung carcinoma (1); lymph node metastasis (1); oesophageal cancer (1); renal cell carcinoma (1).